HMGB1 (high mobility group box 1)
Diseases named in the same sentence as HMGB1 in open-access papers (continued):
Sharing a sentence is not in itself a finding about the gene and the disease.
prostate (2 papers, 2017 to 2019). "Also, HMGB1 may regulate AR either by acting as a co-activator of AR or indirectly associating with RAGE signaling in prostate oncogenesis." (PMID 31410208, 2019). "A number of other kinases, enzymes and transcription factors with recognized roles in prostate carcinogenesis and cancer progression were found to contribute to signalling through PI3K/AKT, PPAR, ERK5, IL-6 and HMGB1." (PMID 28098159, 2017).
prostate adenocarcinoma (2 papers, 2021 to 2025). "We also analysed which genes encoding the proteins found in the HMGB1 interactomes are more frequently highly expressed in tumour samples from prostate adenocarcinomas, and we found among them RRS1 and BOP1, both important regulators of ribosome biogenesis." (PMID 34572914, 2021). "Interestingly, HMGB1 silencing in PC-3 cells results in dysregulation of genes involved in these processes too, mimicking the dysregulation observed in tumours from patients diagnosed with ovary cystadenocarcinoma and prostate adenocarcinoma (acinar type) with lower levels of HMGB1." (PMID 34572914, 2021).
retinal (2 papers, 2015 to 2017). "Exogenous HMGB1 exacerbated retinal ischemic damage, RGC loss, and inhibition of endogenous HMGB1 significantly reduced the severity of disease." (PMID 26224068, 2015). "The level of phosphor-NF-κB p65 increased or decreased to a lesser degree in ischemic retinal tissue in response to the addition of rHMGB1 or HMGB1 inhibitor, indicating that HMGB1 activated the nuclear translocation of NF-κB in retinal IR injury." (PMID 26224068, 2015). "In this study, we hypothesized that inhibition of high mobility group box 1 (HMGB1) could restore normal insulin signaling in retinal endothelial cells (REC) grown in high glucose, as well as protect the retina against ischemia/reperfusion (I/R)-induced retinal damage." (PMID 28542588, 2017). "HMGB1 led to the activation of canonical NLRP3 and non-canonical caspase-8 inflammasomes and the processing of IL-1β in retinal IR injury." (PMID 26224068, 2015).
retinal ischemia (2 papers, 2015 to 2021). A ischemic disease that involves the retina. "Additionally, retinal ischemia damage rapidly initiated the release of HMGB1 at 6 h after reperfusion and peaked at 48 h in the protein level." (PMID 26224068, 2015).
retinitis pigmentosa (2 papers, 2022 to 2025). Retinitis pigmentosa (RP) is an inherited retinal dystrophy leading to progressive loss of the photoreceptors and retinal pigment epithelium and resulting in blindness usually after several decades. "In addition, postmortem eyes from retinitis pigmentosa (RP) patients exhibited necrotic features together with higher levels of high mobility group-1 (HMGB1) protein in the vitreous of RP patients, reflecting necrotic cell death in RP." (PMID 39448868, 2025).
rhabdomyosarcoma (2 papers, 2020 to 2024). A rare aggressive malignant mesenchymal neoplasm arising from skeletal muscle. "We showed that CAP induced the death of MX−7 mouse rhabdomyosarcoma cells with the hallmarks of immunogenic cell death (ICD): calreticulin and heat shock protein 70 (HSP70) externalization and high-mobility group box 1 protein (HMGB1) release." (PMID 32698492, 2020).
rhegmatogenous retinal detachment (2 papers, 2011 to 2012). Retinal detachment secondary to retinal tear or break. "In this study, HMGB1 and MCP-1 were detected in all vitreous samples from patients with rhegmatogenous retinal detachment (RD)." (PMID 21850157, 2011).
rhinosinusitis (2 papers, 2015 to 2021). "The present study investigates the expression of RAGE and HMGB1 in epithelial cells of sinonasal mucosa (SM) obtained from the patients with recalcitrant CRSwNP vs. normal controls (NC) and discusses the role of RAGE and HMGB1 in the pathogenesis of recalcitrant rhinosinusitis and disease severity." (PMID 25503556, 2015).
Rotavirus infection (2 papers, 2014 to 2025). Infection with any of the rotaviruses. "It has been shown that the levels of TLR2 and TLR4 on various cells are increased during the initiation and modulation of the immune response to rotavirus infection, and that HMGB1 acts as a pro-inflammatory cytokine that causes persistent inflammatory responses via activation of TLR2 and TLR4." (PMID 24651485, 2014). "In this study, we aimed to determine the effects of HSP-27, Caspase-3, IL-2, γ-H2AX, HMGB-1, SP-D, and GDH on the pathogenesis of rotavirus infection by using biomarkers of lung and liver injury in neonatal diarrheic calves naturally infected with rotavirus, both in vivo and postmortem." (PMID 41515946, 2025).
scleroderma (2 papers, 2019 to 2022). Scleroderma is a rare autoimmune connective tissue disorder characterized by abnormal hardening of the skin and, sometimes, other organs. "In another bleomycin-induced mouse scleroderma model, local M2-macrophage-derived HMGB1 contributed to the development of tissue fibrosis by producing α2-antiplasmin via RAGE receptors on fibroblasts." (PMID 35250993, 2022). "In the bleomycin-induced mouse scleroderma model, the HMGB1 and sRAGE levels in peripheral blood were increased compared with control mice." (PMID 35250993, 2022). "HMGB1-bearing vesicles are extremely abundant in the blood of scleroderma patients, and when injected in mice recapitulate some aspects of scleroderma." (PMID 31819042, 2019).
Takayasu arteritis (2 papers, 2015 to 2022). A rare inflammatory large-vessel vasculitis primarily affecting the aorta and its major branches, but also other large vessels, causing stenosis, occlusion, or aneurysm. "One study found that HMGB1 levels did not change in healthy controls and LVV patients, as well as during disease activity and remission, while another found HMGB1 levels increased in patients with Takayasu arteritis." (PMID 35250993, 2022).
tauopathies (2 papers, 2021 to 2023). "To investigate the relationship between APOE4 and HMGB1 in the setting of tauopathy, we utilized a compound mouse model with humanized APOE and transgenic Tau-P301S expression." (PMID 37863057, 2023). "We further exemplify the beneficial effects of HMGB1 inhibitor treatment on APOE4-tauopathy mice utilizing snRNA-seq." (PMID 37863057, 2023). "In the present study, we demonstrate in a tauopathy mouse model that HMGB1 plays a central role in the induction and exacerbation of APOE4-driven AD pathologies." (PMID 37863057, 2023). "Treatment of APOE4-tauopathy mice with HMGB1 inhibitors effectively blocked the intraneuronal translocation and release of HMGB1 and ameliorated the development of APOE4-driven gliosis, Tau pathology, neurodegeneration, and myelin deficits." (PMID 37863057, 2023). "These further suggest that treatment of APOE4-tauopathy mice with HMGB1 inhibitors diminishes the presence of DAM subclusters while enriching for disease-protective microglial subclusters." (PMID 37863057, 2023). "Taken together, these data strongly indicate that treatment of APOE4-tauopathy mice with HMGB1 inhibitors diminishes the presence of DAA subclusters while enriching for disease-protective astrocyte subclusters." (PMID 37863057, 2023). "Based on our findings that APOE4 is a potent driver of HMGB1 intracellular translocation and release from neurons, we tested the therapeutic efficacy of HMGB1 inhibitors in combating APOE4-driven AD pathogenesis in the context of tauopathy." (PMID 37863057, 2023). "Single-nucleus RNA sequencing revealed that treatment with HMGB1 inhibitors diminished disease-associated and enriched disease-protective subpopulations of neurons, microglia, and astrocytes in APOE4-tauopathy mice." (PMID 37863057, 2023). "To further analyze the effects of HMGB1 inhibitor treatment in APOE-tauopathy mice, we performed single-nucleus RNA sequencing (snRNA-seq) on hippocampi isolated from 9.5-month-old PS19-E4 and PS19-E3 mice that underwent a 12-week treatment with the HMGB1 inhibitors or saline." (PMID 37863057, 2023). "We next examined whether APOE4 promotes intracellular translocation of HMGB1 in human brains to validate our observations in tauopathy mouse models." (PMID 37863057, 2023). "The findings identified that p-tau has a triggering role in the modulation of neuroinflammation and spatial memory in an NLRP3-dependent manner, and suggest that treatment with HMGB1 inhibitors may be a better therapeutic strategy for tauopathies." (PMID 34539383, 2021). "To further dissect the relationship between HMGB1, APOE genotype, tauopathy, and aging, we assessed the extent of neuronal HMGB1 translocation in 6-month-old PS19-E4 and PS19-E3 mice." (PMID 37863057, 2023). "This illustrates that HMGB1 translocation requires the coexistence of both APOE4 and tauopathy, as observed in the PS19-E4 mice." (PMID 37863057, 2023). "Here, we report in a tauopathy mouse model that APOE4 promoted the nucleocytoplasmic translocation and release of high-mobility group box 1 (HMGB1) from hippocampal neurons, which correlated with the severity of hippocampal microgliosis and degeneration." (PMID 37863057, 2023). "Ultimately, the goal of the study is to understand the role of HMGB1 in APOE4-driven AD pathogenesis and to identify new therapeutic approaches combating APOE4-related AD and other tauopathies." (PMID 37863057, 2023). "We demonstrate that treatment with two well-characterized small-molecule inhibitors of HMGB1, EP and GA,70–72 prevents intraneuronal HMGB1 translocation and release and leads to a striking reduction in a variety of prominent AD pathologies in APOE4-tauopathy mice." (PMID 37863057, 2023). "Our pharmacological study also shows that treatment with HMGB1 inhibitors led to significant reductions of AD-related pathologies only in APOE4-tauopathy mice and not in APOE3-tauopathy mice." (PMID 37863057, 2023).
tauopathies (continued). "Taken together, these findings indicate that HMGB1 plays an essential role in the pathogenic mechanism of APOE4-promoted gliosis and subsequent degeneration and that HMGB1 inhibitors represent a promising therapeutic agent to combat APOE4-driven AD and other tauopathies." (PMID 37863057, 2023). "This illustrates that HMGB1 is able to induce persistent gliosis in young PS19-E4 mice even several weeks post-injection and suggests that the HMGB1 release from hippocampal cells represents a mechanism by which APOE4 promotes gliosis in the context of tauopathy." (PMID 37863057, 2023).
thymic carcinoma (2 papers, 2014 to 2022). Thymic carcinoma (TC) is a type of thymic epithelial neoplasm characterized by a high malignant potential. "HMGB1 nuclear staining was strongest in A and AB, and gradually less in B1 = B2>B3>thymic carcinoma (p<0.001)." (PMID 24705787, 2014). "Conversely, HMGB1 cytoplasmic staining intensities were as follows: A and AB (none), B1 (strong), B2 (moderate), B3 and thymic carcinoma (weak); (p<0.001)." (PMID 24705787, 2014).
toxoplasmosis (2 papers, 2017 to 2024). A parasitic disease contracted by the ingestion or fetal transmission of toxoplasma gondii. "To investigate whether HMGB1 contributes to the toxoplasmosis lesions, we examined HMGB1 changes during T. gondii infection." (PMID 28484433, 2017).
transitional cell carcinoma (2 papers, 2020). A malignant neoplasm arising from the transitional epithelium, usually affecting the urinary bladder, ureter, or renal pelvis. "Besides, our previous study found that urothelial cell carcinoma (UCC) patients who carry at least one T allele of the HMGB1 rs1045411 polymorphism had a lower risk and less invasive disease." (PMID 33023053, 2020). "To this purpose, we have screened Y2H libraries, prepared from SKOV-3 cells and from tumor tissue diagnosed as primary transitional cell carcinoma (TCC) of the ovary, with HMGB1 and HMGB2 baits." (PMID 32867128, 2020).
ventilator-associated pneumonia (2 papers, 2016 to 2020). Serious INFLAMMATION of the LUNG in patients who required the use of PULMONARY VENTILATOR. "We previously demonstrated increased HMGB1 concentrations in BALF from the infected site of patients with community-acquired pneumonia, in BALF of patients with ventilator-associated pneumonia and in BALF from mice intranasally infected with influenza A virus." (PMID 26824892, 2016).
viral myocarditis (2 papers, 2016 to 2018). Myocarditis that is caused by an infection with a viral agent. "Recent studies suggest that ethyl pyruvate protects against coxsackie virus B3-induced acute viral myocarditis by suppression of HMGB1/RAGE/NF-κB pathway." (PMID 29420582, 2018).
Zika (2 papers, 2022). "During ZIKV infection, the accumulation of nuclear HMGB1 was reduced to 51% at 24 h.p.i (P < 0.01), to 7.2% at 48 h.p.i (P < 0.001) and 0% at 72 h.p.i." (PMID 35058496, 2022). "In conclusion, current findings suggest that ZIKV infection triggers HMGB1 translocation from the nucleus to the cytoplasm and extracellular release in a time- and MOI-dependent manner." (PMID 35058496, 2022). "Further in vivo investigation is also important to provide a better understanding of HMGB1’s role in ZIKV infection." (PMID 35058496, 2022). "In contrast, the ZIKV infection at MOI of 1 significantly increased the extracellular HMGB1 levels at 48 h.p.i (1074.75 ± 91.25 pg/mL, P < 0.001) and 72 h.p.i (1397.25 ± 13.75 pg/mL, P < 0.001), in comparison to those of the mock-infected cells." (PMID 35058496, 2022). "Treatment of Huh7 cells with dexamethasone, a well-known anti-inflammatory drug, significantly reduced ZIKV infection and the extracellular HMGB1 levels." (PMID 35058496, 2022). "HMGB1’s role in ZIKV infection was also explored using treatment with dexamethasone, an immunomodulatory drug, and HMGB1-knockdown (shHMGB1) Huh7 cells." (PMID 35058496, 2022). "Additional research is needed to elucidate the potential protective role of extracellular HMGB1 on neighboring cells during ZIKV infection." (PMID 35058496, 2022). "In the study, it was demonstrated that the ZIKV infection induced translocation of HMGB1 from the nucleus to the cytoplasm and subsequently released extracellularly from the infected Huh7 cells." (PMID 35058496, 2022). "On the other hand, the ZIKV infection resulted in increased level of HMGB1 in the cytoplasm by 11% at 24 h.p.i (P < 0.001), 39% at 48 h.p.i (P < 0.001) and 99% at 72 h.p.i." (PMID 35058496, 2022). "In the present study, the potential role of high mobility group box 1 protein (HMGB1) in ZIKV infection was investigated." (PMID 35058496, 2022). "Although HMGB1 has been found to have significant effects on various virus replication, the role of HMGB1 in ZIKV infection remains largely unknown." (PMID 35058496, 2022). "Similarly, our study showed that ZIKV infection could induce HMGB1 nuclear-to-cytoplasmic translocation and release in a time-dependent manner, most likely through the similar mechanisms described." (PMID 35058496, 2022). "After ZIKV infection at MOI of 1, the Huh7 cells were treated with 0, 5, 80 and 150 μM of dexamethasone and the HMGB1 release from the infected cell and virus titers were assessed at 72 h.p.i." (PMID 35058496, 2022). "The following study aimed to examine the dynamic of HMGB1 expression following ZIKV infection in vitro and its potential role in the pathogenesis of Zika with interest in the liver infection using the liver originated Huh7 hepatoma cells." (PMID 35058496, 2022).
abscess (1 paper, 2025). An inflammatory process characterized by the accumulation of pus within a newly formed tissue cavity which is the result of a bacterial, fungal, or parasitic infection or the presence of a foreign body. "In contrast, HMGB1 (B = 0.194; p < 0.001; OR 1.21; 95% CI 1.09–1.35) and kallistatin (B = −0.930; p < 0.001; OR 0.395; 95% CI 0.24–0.648) were independent determinants of abscess formation." (PMID 41153226, 2025).
actinic keratosis (1 paper, 2023). A precancerous lesion of the skin composed of atypical keratinocytes. "HMGB1 can be found in conditioned media of senescent cells and reduced levels of HMGB1 and lamin B1 have been found within the epidermis of precancerous actinic keratosis lesions." (PMID 38074322, 2023).
actinomycosis (1 paper, 2013). Actinomycosis is a chronic bacterial infection that commonly affects the face and neck. "HMGB1 mRNA and protein levels were significantly increased in the hepatic actinomycosis tissue compared with the control and HCC tissue." (PMID 23351605, 2013). "In the actinomycosis-affected cells, staining in both the cytoplasm and nucleus was enhanced, suggesting increased HMGB1 protein levels throughout the hepatic cell in this patient with primary hepatic actinomycosis." (PMID 23351605, 2013). "The serum HMGB1 concentration in the patient who had actinomycosis was 8.5ng/mL, 2.1±0.9ng/mL in the control group and 5.2±0.7ng/mL in the HCC group." (PMID 23351605, 2013). "However, the serum HMGB1 level in the patient who had actinomycosis was significantly higher than the level in the patients who had HCC." (PMID 23351605, 2013). "The expression of HMGB1 in hepatic actinomycosis was significantly high." (PMID 23351605, 2013). "The HMGB1 level in the patient who had actinomycosis was higher than the control and HCC groups." (PMID 23351605, 2013). "HMGB1 may be useful in the differential diagnosis of hepatic actinomycosis." (PMID 23351605, 2013). "Although the expression of HMGB1 increased in the patients who had HCC and the patient with actinomycosis, the distribution of HMGB1 was different." (PMID 23351605, 2013). "Based on immunohistochemistry, we clearly showed that HMGB1 was distributed mainly in the nucleus in the patients who had HCC, but in the patient with actinomycosis the expression of HMGB1 increased in the cytoplasm and nucleus." (PMID 23351605, 2013).
adenocarcinoma of the ampulla of Vater (1 paper, 2019). "The present study suggests that HMGB1 is a prognostic factor and potential biomarker for survival in patients not treated with adjuvant chemotherapy with adenocarcinoma of the ampulla of Vater not treated with adjuvant chemotherapy." (PMID 31399104, 2019).
adenomyosis (1 paper, 2025). The growth of endometrial tissue inside the muscular wall of the uterine corpus. "Adenomyosis demonstrates paradoxical Treg deficit with elevated Th17/Treg ratio and dominant HMGB-1/TLR4 activation (particularly in secretory phase), creating distinctly pro-inflammatory microenvironment." (PMID 41488658, 2025). "Besides HMGB-1, increased fractalkine (CX3CL1) chemokine expression is found in adenomyosis endometrium, attracting immune cells (monocytes, macrophages, NK and T cells) through CX3CR1 receptor." (PMID 41488658, 2025).
adult T-cell leukemia (1 paper, 2014). "The present study reports high plasma HMGB1 levels in patients with adult T-cell leukemia [ATL; which is caused by infection with human T-cell lymphotropic virus type I (HTLV-I)] compared with normal controls." (PMID 24944700, 2014).
alopecia areata (1 paper, 2019). Loss of scalp and body hair involving microscopically inflammatory patchy areas. "But HMGB1 effect in alopecia areata results from its immunostimulating action, which eventually induces the apoptosis of the hair follicle keratinocyte driven by autoimmune response." (PMID 31040377, 2019). "Counterintuitively, previous studies in alopecia areata have shown the contradictory effect of HMGB1 on hair follicle growth." (PMID 31040377, 2019).
ampullary cancer (1 paper, 2019). "The present study is the first to examine the association of HMGB1 expression and ampullary cancer." (PMID 31399104, 2019). "Based on these results, HMGB1-targeted therapy for ampullary cancer with HMGB1 overexpression is promising." (PMID 31399104, 2019). "However, the relationship between HMGB1 overexpression and survival in ampullary cancer has not yet been elucidated." (PMID 31399104, 2019). "However, the prognostic value of HMGB1 in ampullary cancer has not been studied." (PMID 31399104, 2019).